TSLP (thymic stromal lymphopoietin)
Diseases named in the same sentence as TSLP in open-access papers (continued):
Sharing a sentence is not in itself a finding about the gene and the disease.
asthma (continued). "Another bronchoscopy study (CASCADE) aims to better understand the mechanisms of TSLP blockade by investigating the effects of tezepelumab on the number of inflammatory cells in endobronchial biopsies from adults with inadequately controlled moderate-to-severe asthma." (PMID 35572064, 2022). "TSLP is a cytokine produced by stromal and endothelial cells after cellular damage and allows the maturation of dendritic cells and release of chemokines by monocytes, so far found to be involved in the pathogenesis of several Th2-oriented diseases, in particular asthma." (PMID 34944487, 2021). "In addition to TSLP, IL-33 and IL-25 may also represent further emerging targets for novel anti-asthma treatments." (PMID 34572294, 2021). "In this prospective observational study, we demonstrated that previous history of severe-to-serious exacerbation, baseline serum tryptase and TSLP levels, and blood eosinophil counts could independently predict the future development of exacerbation in patients with severe asthma." (PMID 33875671, 2021). "The effect of TSLP may also be different for the production of IgA1 and IgA2, which is worth further study since especially IgA2 levels may be diminished in patients suffering from asthma and eczema." (PMID 33808333, 2021). "In conclusion, we show that the long and short form of TSLP differentially regulate IgA production, which may help explain the mechanisms behind the development and exacerbations of asthma and support the effectiveness of therapeutic interventions targeting aberrant TSLP production." (PMID 33808333, 2021). "Therefore, TSLP, IL-33, and IL-25 represent suitable targets for add-on therapies of severe asthma." (PMID 34572294, 2021). "Furthermore, whether the strategy to reduce serum TSLP levels, serum tryptase levels, or blood eosinophil counts in these patients with severe asthma can reduce future development of asthma exacerbation remains to be tested." (PMID 33875671, 2021). "In addition, thymic stromal lymphopoietin (TSLP) can induce airway inflammation in asthma." (PMID 32727619, 2020). "Importantly, anti-TSLP (tezepelumab) has reached phase IIb clinical trials in adults, showing a significant reduction in the annual asthma exacerbation rate compared with placebo in patients with severe, uncontrolled asthma." (PMID 32020335, 2020). "Several experimental and clinical studies have established a correlation between LPS pre-exposure and asthma phenotype abrogation, with our present study attempting to determine the changes occurring in this context in the pro-allergic cytokines secreted by the epithelium, such as TSLP." (PMID 32379832, 2020). "Therefore, blocking TSLP in patients with OCS-dependent asthma may potentially reduce TSLP-mediated corticosteroid insensitivity, permitting reductions in or cessation of OCS treatment." (PMID 33050928, 2020). "Thus, epithelial cell senescence induced by the downregulation of ITGB4 or increased TSLP leading to airway epithelium dysfunction, might be an important mechanism of asthma pathogenesis." (PMID 32117985, 2020). "Considering the profound role of TLSP, IL-33, and IL-17A signaling in obstructive lung disease pathobiology, we sought to investigate whether the interactions between epithelium and macrophages impact TSLP, IL-33, and IL-17A expression in DCs in asthma and COPD." (PMID 32842623, 2020). "The study aimed to evaluate the expression of TSLP, IL-33, and IL-17A in human monocyte derived dendritic cells (moDCs) co-cultured with respiratory epithelium and monocyte derived macrophages (moMφs) in asthma, chronic obstructive pulmonary disease (COPD) and healthy controls." (PMID 32842623, 2020). "Interestingly, genome-wide association studies of asthma have identified RORα (a critical transcription factor for ILC2 development), as well as TSLP, IL-33 and the IL33-receptor (IL1RL1, ST2) as asthma susceptibility genes, supporting the importance of this pathway for asthma." (PMID 31024538, 2019).
asthma (continued). "TSLP may play a fundamental role in the innate–adaptive interface in the pathology of asthma." (PMID 31284537, 2019). "TSLP has been recognized as a primary instigator of allergic inflammation at the dendritic and epithelial cell interface and has been shown to play an important role in innate immune response by inducing the differentiation of T‐helper type 2 (Th2) effector cells in asthma patients." (PMID 31290290, 2019). "Anti-TSLP agents are undergoing trials in asthma and might be considered in EGPA." (PMID 31719529, 2019). "Targeting TSLP may be interesting because of its upstream role in the asthma cascade." (PMID 31395084, 2019). "In particular, polymorphisms in the thymic stromal lymphopoietin (TSLP) gene increase the risk of atopic dermatitis, food allergy, and asthma, whereas polymorphisms in the interleukin (IL) 33 gene predispose patients to atopic dermatitis and promote the subsequent development of asthma." (PMID 31438462, 2019). "The authors suggested that TSLP could be a therapeutic target in asthma." (PMID 30057581, 2018). "In this model, the sub-epithelial TSLP/CCL11/eotaxin-1 responses of the asthmatic bronchial smooth muscle might underlie the presence of airway wall eosinophilc infilitration, one of the most striking features in the pathology of severe asthma." (PMID 25546419, 2014). "Thus, airway epithelial cells are also active players in the pathogenesis of asthma through epithelial cytokines including IL-33, TSLP, and IL-25, which are produced and released by epithelial cells in response to various exogenous stimuli or by cellular damage." (PMID 23496815, 2013). "Thus, it is possible that the lack of an association between the TSLP gene and AR susceptibility noted in our study is an accurate reflection of the real-life situation, because the TSLP gene is associated with asthma but not AR." (PMID 22973903, 2012). "TSLP-mediated Th17 cell commitment under Th2-polarizing conditions may be involved in the development of an inflammatory mixture of Th2 and Th17 cells, a unique profile that resembles severe asthma." (PMID 23194010, 2012). "However, with respect to the association between TSLP polymorphisms and AR, the study by Bunyavanich and colleagues indicated that TSLPSNP rs1837253 was associated with reduced odds for AR in boys with asthma." (PMID 22973903, 2012). "We genotyped 15 single nucleotide polymorphisms (SNPs) in TSLP, OX40L, IL7R, and RXRα in three independent cohorts: 592 asthmatic Costa Rican children and their parents, 422 nuclear families of North American children with asthma, and 239 Swedish children with asthma." (PMID 21244681, 2011). "To determine whether TSLP is required for this susceptibility, we deleted the TSLP receptor in RBP-jCKO mice and showed that this genetic manipulation blocked the development of asthma in animals with persistent AD-like pathology and inflammation." (PMID 19557146, 2009). "On the basis of these observations and that localized TSLP overexpression in lung epithelium is capable of inducing asthma, we have articulated an alternative hypothesis: TSLP may be a systemic signal that sensitizes the animals to allergen exposure in the lung." (PMID 19557146, 2009). "Importantly, overexpression of TSLP in AECs induces experimental asthma in mice." (PMID 18724870, 2008). "Thymic stromal lymphopoietin (TSLP) is a key innate cytokine that promotes bronchial inflammation in both T2-high and T2-low asthma, thus representing a suitable therapeutic target." (PMID 41693791, 2026). "For example, in a model of allergen-induced experimental asthma in ST2KO mice, deletion of ST2 led to elevated TSLP production which in turn stimulated the emergence of IL-9-producing ILC2 cells." (PMID 41465219, 2025). "Cytokines like IL-25, IL-31, IL-33, and thymic stromal lymphopoietin (TSLP), secreted by epithelial cells, are known to induce or amplify type 2 inflammation, resembling patterns seen in allergic rhinitis or asthma." (PMID 40217916, 2025).
asthma (continued). "Thymic stromal lymphopoietin (TSLP), IL-33, and IL-25 are epithelial-derived proinflammatory alarmin cytokines that drive inflammatory airway diseases such as asthma and chronic obstructive pulmonary disease (COPD)." (PMID 41409758, 2025). "We showed how this BsAb potently neutralized signaling from TSLP, IL-4, and IL-13; reduced inflammatory responses in human cell-based assays; and provided broader efficacy in a TSLP/OVA-induced asthma model compared with single-pathway blockade." (PMID 41294800, 2025). "Taken together, our results demonstrate that females with asthma exhibit higher TSLP and sST2 levels in the airways but lower ST2L on ILC2s compared with males with asthma." (PMID 40022441, 2025). "Among the currently available biologics, tezepelumab is the first to target thymic stromal lymphopoietin (TSLP), a cytokine involved in upstream asthma inflammation." (PMID 40861628, 2025). "This is consistent with previous work showing that elevated TSLP in lungs correlates with increased AHR in both mouse models and human asthma, and that neutralizing TSLP or downstream cytokines like IL-4 and IL-13 mitigates AHR and airway inflammation." (PMID 41259396, 2025). "NECs cannot avoid transmitting information via CD4+CD25+Foxp3+ Tregs through TSLP/TSLPR, similar to the lower airway in asthma." (PMID 40051629, 2025). "Abbbreviations: μL, microliter; ACQ‐6, six‐item asthma control questionnaire; BEC, blood eosinophil count; FeNO, fractional exhaled nitric oxide; ppb, parts per billion; TSLP, thymic stromal lymphopoietin." (PMID 40365686, 2025). "Measurements of TSLP levels were then examined in serum, BALF, and lung tissue of different stages of mouse asthma models to confirm and validate the observations from the study population." (PMID 40503233, 2025). "In future research, we will further explore the relationship between miR‐27a‐3p and AICDA, TSLP, EDNRA, and other asthma‐related genes and their expression levels and clinical roles in the serum of children with BA." (PMID 37385291, 2025). "Further, novel humanized anti-TSLP monoclonal antibodies, such as TAVO101, are also being developed for use in the treatment of TSLP-related disorders, such as asthma and psoriasis." (PMID 40283665, 2025). "In asthma, over 212 genomic loci have been identified to date, including loci harboring GSDMB/ORMDL, HLA, TSLP, IL1RL1/Il18R, and IL3310,15–18, confirming the important role of type 2 inflammatory pathways." (PMID 41213931, 2025). "Therefore, blocking TSLP signalling within the epithelium microenvironment may be an important mechanism in directing the early immune response to viral infections and preventing the initiation of virus-induced asthma exacerbations." (PMID 40745660, 2025). "Tezepelumab is a human monoclonal antibody that blocks thymic stromal lymphopoietin (TSLP), an upstream epithelial cytokine involved in asthma pathogenesis." (PMID 40564060, 2025). "Bosakitug (ATI-045, TQC2731) is a humanized anti-TSLP monoclonal antibody currently in development for atopic dermatitis (NCT07011706), asthma (NCT06829784), and COPD (NCT06707883)." (PMID 41409758, 2025). "Accordingly, this study aimed to investigate the involvement of TSLP and TSLPR expression in CRSwNP, CRSwNP with asthma, and N-ERD." (PMID 39940994, 2025). "TSLP immunoreactivity and ILC2 share the same localization in the airways, and a close relationship has been found between TSLP amount and ILC2 counts in nasal biopsies obtained from subjects with severe asthma and chronic rhinosinusitis (CRS)." (PMID 41321706, 2025). "Tezepelumab is a biologic that inhibits thymic stromal lymphopoietin (TSLP), currently approved for severe asthma." (PMID 41124071, 2025). "As both elevated TSLP and ILC2 numbers indicate a type 2 response, we measured the type 2 cytokine IL‐13 in bronchial lavage and found that females with asthma exhibited higher levels of IL‐13 than males with asthma." (PMID 40022441, 2025).
asthma (continued). "Tezepelumab (TEZ), an anti-thymic stromal lymphopoietin (TSLP) monoclonal antibody, has demonstrated broad anti-inflammatory effects in severe asthma, including reduced exacerbations and type 2 biomarkers, regardless of the baseline eosinophil level." (PMID 41409935, 2025). "The concentrations of cytokines such as IL-4, IL-5, IL-13, and TSLP in serum, sputum, and bronchoalveolar lavage fluid (BALF) in asthma have been reported to range from 1 to 100 pg/ml (approximately 0.7–70 pM)." (PMID 39624446, 2024). "The cytokine thymic stromal lymphopoietin (TSLP), derived from epithelial cells, is involved in the initiation and persistence of asthma inflammatory pathways." (PMID 38536788, 2024). "Increasing evidence indicates that biological therapies targeting IgE, IL-5/IL-5Rα, TSLP and IL-33/ST2 can improve not only clinical symptoms but also certain features of airway remodelling in asthma." (PMID 38609094, 2024). "TSLP and ER stress (PERK) mRNA expression positively correlates in bronchial biopsies from participants with asthma, particularly in neutrophilic asthma." (PMID 38469627, 2024). "Only recently, tezepelumab, a human monoclonal antibody that binds specifically to thymic stromal lymphopoietin (TSLP) and targets multiple disease pathways, including T2-low severe asthma, was adopted in clinical practice." (PMID 39200892, 2024). "It works by blocking thymic stromal lymphopoietin (TSLP), an epithelial cytokine that plays a crucial role in initiating and sustaining airway inflammation in asthma." (PMID 39364473, 2024). "In addition, the release of TSLP leads to a proliferation of the bronchial epithelium and nasal epithelium through the activation of fibroblasts, which leads to smooth muscle hypertrophy and increased remodeling, typical of advanced stages of asthma and nasal polyposis." (PMID 38892164, 2024). "Elevated levels of TSLP, IL-25, IL-33 and the IL-33 receptor serum stimulation-2 (ST2) in the serum and bronchial tissue of patients with asthma have also been found to correlate with T2 inflammation and disease severity." (PMID 38453256, 2024). "Epithelium-derived factors (TSLP, IL-33, CCL2) are also known to induce DC migration and maturation, especially of moDCs in severe asthma." (PMID 39244793, 2024). "Thymic stromal lymphopoietin (TSLP) is integral to inducing innate and T helper two cell inflammation that leads to clinical symptoms of asthma." (PMID 39076593, 2024). "Meanwhile, TSLP improves the survival and longevity of ILC2s, thus prolonging the effect of ILC2 in asthma pathogenesis." (PMID 39076593, 2024). "Anti-TSLP and anti-IL5 were the most frequently used biologics for patients with type 2 low asthma (14% and 9%, respectively); however, most (70%) type 2 low phenotype patients were not treated with biologic agents." (PMID 38637825, 2024). "In fact, inhibitors of thymic stromal lymphopoietin (TSLP), a cytokine mainly produced by AECs in the lungs, have emerged as therapeutic agents for asthma." (PMID 38451292, 2024). "In asthma models, HDM-activated PAR2 increases expression of IL-33 and thymic stromal lymphopoietin (TSLP) from bronchial epithelial cells." (PMID 39416784, 2024). "Increased expression of TSLP has been found in bronchial mucosa and bronchoalveolar lavage fluid (BALF) of severe asthma patients." (PMID 38469627, 2024). "summarized in their review the crucial role of thymic stromal lymphopoietin (TSLP), an epithelial cytokine (alarmin), in the pathogenesis of asthma and the therapeutic potential of anti-TSLP monoclonal antibodies in asthma." (PMID 39483464, 2024). "By blocking TSLP from binding to its receptors, TZP reduces TSLP-driven immune activation across various asthma endotypes." (PMID 39552062, 2024).
asthma (continued). "However, while asthma is usually associated with eosinophils, TH2 cells, and/or mast cells, and COPD is commonly linked to TH1 cells, neutrophils, and macrophages, in COPD protein levels and TSLP mRNA were elevated in the bronchial epithelium compared with the controls." (PMID 36830972, 2023). "Another anti-TSLP drug, CSJ117, a neutralizing antibody fragment, is currently being tested in an inhaled formulation in patients with severe uncontrolled asthma (NCT04410523)." (PMID 37199256, 2023). "Quantitatively, higher concentrations of TSLP were also detected in infants with RSV + RV coinfection (p = 0.01), ICU admission (p = 0.01), those with siblings with asthma/atopy (p = 0.004), and first-degree family history of atopy (p < 0.001)." (PMID 36694181, 2023). "TSLP can also activate mast cells, eosinophils, and ILC2 cells, all are known for asthma pathogenesis." (PMID 36832296, 2023). "We identified genetically driven pathways regulating eosinophilia in asthma, with two genes (IL4R, TSLP) targeted by drugs currently available for eosinophilic asthma." (PMID 37186423, 2023). "Undoubtedly, the magnitude of TSLP in asthma pathogenesis is highlighted by the fact that the FDA recently approved tezepelumab (Tezspire), a human monoclonal antibody that targets TSLP, for SA treatment." (PMID 37108740, 2023). "Tezepelumab is a monoclonal IgG2 antibody that exerts its effect by blocking the interaction between human TSLP and TSLPR and thus reduces the production of different cytokines, which is responsible for various debilitating pathophysiology of asthma." (PMID 36601189, 2023). "In an experimental asthma model, it was revealed that NKT cells express TSLPR and IL-7 receptor, and TSLP was shown to directly act on NKT cells and induce the production of IL-13 and thus to increase airway hyperactivity." (PMID 37108740, 2023). "Causal posterior probability was >80% for colocalization between the NP locus 5q22.1 (TSLP/WDR) and asthma endpoints, and between the CDTA locus 12p13.31 (LTBR) and acute appendicitis." (PMID 36653354, 2023). "Therefore, it could be deduced that TSLP and IL-17A are involved in asthma development." (PMID 36834541, 2023). "JAK inhibitors are an attractive small molecule option given the widespread signaling of cytokines and growth factors using JAK-STAT receptors in asthma, including IL-4, IL-5, IL-13, GM-CSF, IFN-α, IFN-β, IFN-γ, and TSLP." (PMID 37265457, 2023). "The most extensively studied cytokines in this context are the epithelial alarmins IL-33, thymic stromal lymphopoietin (TSLP), and IL-25, which contribute to type 2-high asthma." (PMID 36614093, 2022). "On the other hand, several pro-inflammatory factors are involved in pathological processes of the diseased airway epithelium: IL33, TSLP and TGF-β1 are known regulators in common airway diseases like asthma, allergic rhinitis, COPD or cystic fibrosis." (PMID 35782511, 2022). "TSLP is crucial for differentiating dendritic cell–mediated CD4+ T-cells into Th2 cells, and it is closely related to allergic diseases such as asthma, AD, allergic rhinoconjunctivitis, and eosinophilic esophagitis." (PMID 36235405, 2022). "That’s to say, p38 MAPK is vital for allergen induced epithelial production of IL-25 and thymic stromal lymphopoietin (TSLP), further mediating the type-2 allergic response in asthma." (PMID 35656293, 2022). "Two monoclonal antibodies designed to block TSLP and thus inhibit signaling through TSLPR are being investigated in clinical trials as drugs for the treatment of asthma." (PMID 35572064, 2022). "CCL17 and TSLP concentrations were increased in T2‐high‐FNS and T2‐intermediate asthma compared with healthy controls, but similar across the asthma groups." (PMID 35579040, 2022). "These were in loci previously associated with asthma exacerbations (GSDMB, RAD50, HLA‐DQB1, ADAM33, VDR, and CDHR3) or moderate‐to‐severe asthma (IKZF3, TSLP, MUC5AC, C11orf30, SMAD3, and WDR36)." (PMID 35754128, 2022).